ZC3HAV1 (zinc finger CCCH-type containing, antiviral 1)
Description:
Antiviral protein which inhibits the replication of viruses by recruiting the cellular RNA degradation machineries to degrade the viral mRNAs. Binds to a ZAP-responsive element (ZRE) present in the target viral mRNA, recruits cellular poly(A)-specific ribonuclease PARN to remove the poly(A) tail, and the 3'-5' exoribonuclease complex exosome to degrade the RNA body from the 3'-end. It also recruits the decapping complex DCP1-DCP2 through RNA helicase p72 (DDX17) to remove the cap structure of the viral mRNA to initiate its degradation from the 5'-end. Its target viruses belong to families which include retroviridae, including human immunodeficiency virus type 1, filoviridae: ebola virus (EBOV) and marburg virus (MARV), togaviridae: sindbis virus (SINV) and Ross river virus (RRV). Specifically targets the multiply spliced but not unspliced or singly spliced HIV-1 mRNAs for degradation. [Isoform 1]: Exhibits stronger antiviral activity than isoform 2 against MuLV expression and Semliki forest virus infection. Increased antiviral activity may be due to more efficient targeting to endocytic membranes through S-farnesylation (By similarity). Similarly to isoform 2, prevents HIV-1 infection. [Isoform 2]: Positive regulator of RIGI signaling during the innate antiviral immune response. Associates with RIGI to promote its oligomerization and ATPase activity stimulation, leading to robust activation of IRF3 and NF-kappa-B transcription factors and eventually to the expression of type I IFNs and IFN stimulated genes (ISGs). Similarly to isoform 1, prevents HIV-1 infection.
Synonyms: ARTD13; PARP13; ZAP; ZC3HDC2; FLB6421; FLJ13288; MGC48898; ZC3H2
Tractability: Small molecule: a structure with a bound ligand is known. PROTAC: ubiquitination databases record sites on it; its protein half-life has been measured.
Gene: Protein-coding gene on chromosome 7 (139,043,515 to 139,132,122, reverse strand). Ensembl gene ENSG00000105939.
Subcellular location: Nucleus (Isoform 1); Lysosome; Late endosome; Nucleus (Isoform 2); Cytoplasm; Membrane
Subcellular location (Human Protein Atlas): Cytosol; Golgi apparatus
Pathways (Reactome):
Disease: Signaling by BRAF and RAF1 fusions
Gene Ontology:
Molecular function: cadherin binding; NAD+ binding; NAD+ poly-ADP-ribosyltransferase activity; NAD+-protein mono-ADP-ribosyltransferase activity; protein binding; RNA binding; metal ion binding
Biological process: negative regulation of viral genome replication; positive regulation of mRNA catabolic process; protein poly-ADP-ribosylation; response to virus; positive regulation of RIG-I signaling pathway
Cellular component: cytoplasm; cytosol; late endosome; lysosome; membrane; nucleus
Genetic constraint (gnomAD): Loss-of-function variants: 39 observed, 85.58 expected, observed/expected ratio (o/e) 0.46, 90% interval 0.35 to 0.6. The upper end of that interval is the gene's LOEUF score, 0.6, which puts it in group 2 of 6, group 1 being the genes least tolerant of losing a copy. Missense variants: 950 observed, 1,166.2 expected, observed/expected ratio (o/e) 0.81, 90% interval 0.77 to 0.86. Synonymous variants: 417 observed, 442.63 expected, observed/expected ratio (o/e) 0.94, 90% interval 0.87 to 1.02.
Homologues: Orthologues: chimpanzee ZC3HAV1 (97% identical), macaque ZC3HAV1 (91% identical), dog ZC3HAV1 (65% identical), pig ZC3HAV1 (64% identical), guinea pig ZC3HAV1 (62% identical), rabbit ZC3HAV1 (57% identical), mouse Zc3hav1 (56% identical), rat Zc3hav1 (55% identical). Paralogues in human: PARP12 (26% identical), PARP14 (16% identical), TIPARP (15% identical), ZC3HAV1L (13% identical), PARP9 (11% identical), PARP15 (10% identical), PARP11 (10% identical), PARP10 (8% identical).
Diseases named in the same sentence as ZC3HAV1 in open-access papers:
ZC3HAV1 is named in the same sentence as 32 diseases in open-access papers, as found by Europe PMC text mining. Sharing a sentence is not in itself a finding about the gene and the disease. The quoted sentences say what the papers report.
viral infection (15 papers, 2012 to 2025). "Seven of these acetylated proteins, including DDX3X, PTBD, TRIM56, IPO7, PPID, SHMT2, and ZC3HAV1, have been implicated in innate immunity and viral infection, based on functional annotation using databases such as GO Biological Process, KEGG and reactome." (PMID 39747662, 2025). "First, ZC3HAV1 plays a critical role in the host response to viral infection and functions by promoting the degradation of viral mRNAs44,62." (PMID 38750080, 2024). "We found that the protein expression level of p-IRF3 was higher in ZC3HAV1-overexpressed cells after the viral infection by using ImageJ software." (PMID 32922375, 2020). "The results show that the protein expression level of p-IRF3 was reduced in ZC3HAV1 knockdown cells after the viral infection by using ImageJ software." (PMID 32922375, 2020). "Expression of ZC3HAV1 induced by Sev was upregulated in a virus infection time-dependent manner." (PMID 32922375, 2020). "Previous studies have shown that ZC3HAV1 could repress translation and promote degradation of specific viral mRNAs and thereby suppress the viral infection." (PMID 32922375, 2020). "This has novel implications on the postulated effector functions of Zc3hav1, in response to decorin, as it comprises a link to modulate innate cellular defenses against viral infections, and/or a mechanism to regulate endogenous RNA signaling within the tumor microenvironment." (PMID 23029096, 2012). "Indeed, ZC3HAV1 protein level was consistently increased after the viral infection." (PMID 32922375, 2020). "ZC3HAV1 and TRIM25 were shown to contribute to the up-regulation of type I interferons (IFN) upon viral infection." (PMID 37221558, 2023). "ZC3HAV1 was found to diminish levels of HCMV mRNA and protein, and inhibit the progression of viral infection by mediating degradation of specific viral transcripts." (PMID 37221558, 2023). "One particularly interesting case is provided by the zinc-finger CCCH-type antiviral protein 1 (ZC3HAV1, also known as poly(ADP-ribose) polymerase 13-PARP13), a protein that is known to protect host cells from viral infection and cellular stress." (PMID 26337052, 2015). "Furthermore, we observed that both isoforms of ZC3HAV1, ZAPS and ZAPL, were induced by infections with IAV and Sev, but it appeared that ZAPS other than ZAPL was a potent regulator of IFN-β and MxA expression during the viral infection." (PMID 32922375, 2020).
breast carcinoma (5 papers, 2012 to 2024). "The downregulation of phosphopeptides in genes like ARID1A, EPRS, and ZC3HAV1 in the high relapse-risk breast cancer group offers critical insights into their roles as tumor suppressors and regulatory molecules." (PMID 38745208, 2024). "A breast cancer risk model consisting of 5 AS events was constructed in our study, which was risk score = (TTC39C|44853|AT*− 2.67) + (HSPBP1|52052|AP*− 4.28) + (MAZ|35942|ES*2.34) + (ANK3|11845|AP*1.18) + (ZC3HAV1|81940|AT*1.59)." (PMID 35988113, 2022). "ZC3HAV1, a PARP family enzyme, promotes proliferation and metastasis by regulating KRAS in pancreatic cancer and is involved in facilitating DNA repair and promoting tumorigenesis in breast cancer." (PMID 38745208, 2024). "No data were available in the ONCOMINE for either BMP2K or ZC3HAV1 related to breast cancer." (PMID 23029096, 2012).
liver cancer (3 papers, 2021 to 2024). An epithelial or non-epithelial malignant neoplasm that arises from the liver. "However, the current research on ZC3HAV1 in liver cancer remains limited, and preliminary experiments in liver cancer tissues suggest an elevated expression of this gene." (PMID 39513103, 2024). "Moreover, ZC3HAV1 has been found to engaged with the occurrence of multiple cancers, like liver cancer, colon cancer and bladder cancer." (PMID 34319912, 2021). "Zinc finger CCCH-type containing, antiviral 1 (ZC3HAV1), also known as zinc-finger antiviral protein (ZAP), has been shown to limit the replication of certain viruses, thereby preventing virus-related cancers such as liver cancer and leukemia." (PMID 34926575, 2021).
pancreatic cancer (3 papers, 2021 to 2026). "ZC3HAV1, a PARP family enzyme, has been shown in pancreatic cancer to regulate cell cycle progression by modulating cyclin D1 and CDK2, and to bind KRAS, enhancing its expression and activating ERK signalling to promote proliferation and metastasis." (PMID 41596441, 2026).
colon cancer (2 papers, 2021 to 2024). "In addition, it’s reported in recent studies that ZC3HAV1 is in relation to the development of colon cancer, liver, cancer and bladder cancer, which suggests that ZC3HAV1 may be beneficial to the progression of some cancers." (PMID 34319912, 2021).
colorectal cancer (2 papers, 2025 to 2026). A primary or metastatic malignant neoplasm that affects the colon or rectum. "Among the most significant reQTLs were those for the gene ZC3HAV1, a zinc-finger protein previously implicated in colorectal cancer and innate immune responses." (PMID 41505470, 2026).
HIV-1 infection (2 papers, 2015 to 2025). The type species of lentivirus and the etiologic agent of acquired immunodeficiency syndrome (AIDS). "Finally, we determined that IL-6—a cytokine regulated by DDX3X and ZC3HAV1—also changes its expression levels during the different stages of HIV-1 infection in microglia." (PMID 40429887, 2025). "Additionally, we determined that IL-6, a cytokine regulated by DDX3X and ZC3HAV1, exhibits changes in protein expression levels during both active and persistent HIV-1 infection." (PMID 40429887, 2025).
melanoma (2 papers, 2014 to 2025). A malignant, usually aggressive tumor composed of atypical, neoplastic melanocytes. "A number of BRAF fusions are, however, novel, including ATG7–BRAF in melanoma, as well as ZC3HAV1–BRAF and FAM114A2–BRAF in thyroid cancer." (PMID 25204415, 2014). "Unfortunately, the HT12.4 array utilised in this study does not contain probes for all the ncRNAs identified in our RNA-seq data, but we did observe a significant correlation between expression of ZC3HAV1 and miR-148a and patient survival in primary melanoma tumour samples." (PMID 40654904, 2025).
osteosarcoma (2 papers, 2021 to 2024). A usually aggressive malignant bone-forming mesenchymal neoplasm, predominantly affecting adolescents and young adults. "For the first time, we found that ZC3HAV1 was up-regulated in osteosarcoma cell lines and also osteosarcoma tissues." (PMID 34926575, 2021). "Our results showed that compared with osteoblasts, CPEB3, EIF4E3, RBM34, RPS27L, RPS29 and TDRD6 were down-regulated in U2OS and 143B, while NXT2, TERT, TLR8 and ZC3HAV1 were up-regulated in osteosarcoma cells." (PMID 34926575, 2021). "Consistently, ZC3HAV1 mRNA and protein levels in osteosarcoma tissues were significantly higher than adjacent normal tissues." (PMID 34926575, 2021). "Western blotting showed that compared with normal osteoblasts, ZC3HAV1 protein levels in osteosarcoma cells were significantly up-regulated." (PMID 34926575, 2021). "Finally, we did not use in vitro or in vivo experiments to thoroughly verify our findings, which means that the exact mechanism of ZC3HAV1 involved in osteosarcoma is still unclear." (PMID 34926575, 2021). "Therefore, we further quantified the expression of ZC3HAV1 in normal osteoblasts (hFOB1.19 cells) and 143B and U2OS osteosarcoma cell lines." (PMID 34926575, 2021). "However, the role of ZC3HAV1 in osteosarcoma has not been reported yet." (PMID 34926575, 2021).
Autoimmunity (1 paper, 2023). The occurrence of an immune reaction against the organism's own cells or tissues. "An Italian cohort study indicated an association of the ZC3HAV1 rs3735007 polymorphism with MS, an autoimmune disorder which may have a common immune pathogenesis with VKH disease." (PMID 37221558, 2023). "Given the potential link of ZC3HAV1 as well as TRIM25 with autoimmunity, we presume that genetic polymorphisms in ZC3HAV1 and TRIM25 might confer susceptibility to VKH disease." (PMID 37221558, 2023).
COVID-19 (1 paper, 2023). A disease caused by infection with severe acute respiratory syndrome coronavirus 2. "The clinical importance of mutations in the ZAP-encoding gene, ZC3HAV1, was highlighted in a recent study that linked a mutation in this gene with COVID-19 disease severity." (PMID 37146066, 2023).
glioma (1 paper, 2024). A benign or malignant brain and spinal cord tumor that arises from glial cells (astrocytes, oligodendrocytes, ependymal cells). "The results revealed a positive correlation between the expression of genes such as ZC3HAV1, TIPARP, PARP4, PARP14, and PARP15 and the abundance of various immune cell types in gliomas." (PMID 39724285, 2024).
HCMV infection (1 paper, 2023). "A similar approach could be applied to HCMV infection, as suggested by the discovery of the intracellular zinc finger antiviral protein (PARP13 and ZC3HAV1) and their cofactors (TRIM25) with antiviral activity." (PMID 37894030, 2023).
influenza (1 paper, 2025). An acute viral infection of the respiratory tract, occurring in isolated cases, in epidemics, or in pandemics; it is caused by serologically different strains of viruses (influenzaviruses) designated A, B, and C, has a 3-day incubation period, and usually lasts for 3 to 10 days. "A similar pattern was observed for the MOV10 and ZC3HAV1 genes, host factors that restrict influenza replication; their induction was attenuated by milk in A549 cells." (PMID 41157297, 2025).
lymph node metastasis (1 paper, 2021). "Meanwhile, overexpression of ZC3HAV1 had positive relation with larger tumor size and lymph node metastasis together with overall poor survival of patients with PC." (PMID 34319912, 2021).
multiple sclerosis (1 paper, 2024). A progressive autoimmune disorder affecting the central nervous system resulting in demyelination. "Of particular interest were two expression quantitative trait loci in CD8+ T cells that were fine mapped to multiple sclerosis susceptibility variants in the viral control genes ZC3HAV1 (rs10271373) and IFITM2 (rs1059091)." (PMID 38038362, 2024). "We further describe the first single-cell eQTL analysis of CSF and identify two eQTLs in CD8+ T cells correlated with multiple sclerosis susceptibility, both in genes related to controlling viral responses—ZC3HAV1 and IFITM2." (PMID 38038362, 2024). "In three instances, the credible set for the eQTL included the known multiple sclerosis susceptibility variants: rs3764021 for the expression of CLECL1 in macrophages; rs1059091 for the expression of IFITM2 in CD8+ T cells; and rs10271373 for the expression of ZC3HAV1 in CD8+ T cells." (PMID 38038362, 2024).
uveitis (1 paper, 2023). An inflammatory process affecting a part of or the entire uvea. "Second, we examined only one widespread uveitis entity, it remains to be seen whether the genetic polymorphisms of ZC3HAV1 may confer susceptibility to other types of uveitis." (PMID 37221558, 2023).
VKH disease (1 paper, 2023). "We found a statistically significant increased frequency of the minor A allele of ZC3HAV1 rs7779972 (P = 1.50 × 10− 4, pooled OR = 1.332, 95%CI = 1.149–1.545) in VKH disease as compared with controls by using the Cochran-Mantel-Haenszel test." (PMID 37221558, 2023). "In summary, this study performed in Han Chinese reveals that rs7779972 of ZC3HAV1 has a significant association with VKH disease, thus providing a novel insight into the etiology and pathogenesis of this disease." (PMID 37221558, 2023). "The variant associated with VKH disease identified in our study was rs7779972, located in the intron of ZC3HAV1." (PMID 37221558, 2023). "Our study indicated that the ZC3HAV1 variant rs7779972 might confer susceptibility to VKH disease in Han Chinese." (PMID 37221558, 2023). "In this case-control association study, we examined the association of ZC3HAV1 and TRIM25 genetic polymorphisms with VKH disease in Han Chinese, and observed that the minor A allele and GG genotype of ZC3HAV1 rs7779972 was significantly associated with VKH disease." (PMID 37221558, 2023).
infection (20 papers, 2013 to 2025). The state of being infected such as from the introduction of a foreign agent such as serum, vaccine, antigenic substance or organism. "Feng observed that ZC3HAV1 (chZAP) mRNA showed a two-fold up-regulation in spleen at day 4 post infection of ALV-J, indicating the association between the innate immune factor of chZAP and ALV-J." (PMID 28938603, 2017). "Zc3hav1 deficiency enhanced vesicular stomatitis virus (VSV, a ssRNA virus recognized by RIG-I) infection- or the dsRNA analog poly(I:C) transfection-induced Ifna4 mRNA expression and IRF3 phosphorylation." (PMID 39478149, 2024). "ZC3HAV1 is induced during influenza A/WSN/33 (WSN/H1N1) infection and ectopic expression of ZC3HAV1 inhibits WSN replication." (PMID 36279270, 2022). "In the present study, we detected that sh-RNA-mediated knockdown of ZC3HAV1 expression reduced the induction of IFN-β mRNA in response to the infection of IAV." (PMID 32922375, 2020). "Overexpression of ZC3HAV1 in A549 cells resulted in an increased induction of MxA mRNA, following the infection with the IAV." (PMID 32922375, 2020). "In this study, we found that expression of ZC3HAV1 was significantly induced by infection with influenza A virus (IAV) and Sendai virus (Sev)." (PMID 32922375, 2020). "In this study, we observed that infection with WSN virus significantly upregulated the expression of ZC3HAV1 in A549 cells, indicating that ZC3HAV1 is an influenza virus-inducible host factor." (PMID 32922375, 2020). "The zinc finger antiviral protein (ZAP, also known as ZC3HAV1) was originally discovered in rat as a host antiretroviral factor that prevents cells from infection by Moloney murine leukemia virus (MMLV)." (PMID 23853601, 2013). "Furthermore, the STING inhibitor H-151 reduced IL-6 secretion and counteracted the pronounced differences in IL-6 secretion between Zc3hav1-/- mice and the control mice after infection with HSV-1 or injection of DMXAA." (PMID 39478149, 2024). "Proteins downregulated during later stages of MVA infection showed a strong tendency to self-associate, including nuclear pore components, and a selection of nucleolar proteins associated with ribosome biogenesis (e.g. SURF6, RBM28, RPL7L1, ZC3HAV1, CDK105)." (PMID 38065956, 2023). "In addition, we also observed that expression of ZC3HAV1 was significantly induced by infection with Sev, and increased ZC3HAV1 inhibited the virus replication." (PMID 32922375, 2020). "In addition, we found that infection of Sev can induce the expression of ZC3HAV1 in A549 cells." (PMID 32922375, 2020). "For instance, ZC3HAV1 (the parental gene of VSC3 and VSC6) was significantly upregulated by infection with influenza A virus (IAV) and Sendai virus." (PMID 41181322, 2025). "Of note, we observed that several duck IFN-stimulated genes (ISGs), including IFI35, Mx, ISG15, ZC3HAV1, LGP2, IFITM1, IFITM2, and Viperin, were dramatically upregulated upon DTMUV infection." (PMID 34335626, 2021). "In contrast, during MNV infection, only 5 out of 21 of the cross-core stress granules proteins displayed a high enrichment with G3BP1, namely ZC3HAV1, FXR1 and G3BP2." (PMID 31905230, 2020). "Interference with the endogenous expression of ZC3HAV1 enhanced the replication of influenza virus by impairing the production of IFN-β and MxA, following the infection of influenza virus." (PMID 32922375, 2020). "Then ZC3HAV1 knockdown cells were infected with WSN virus, and RNA extracts were harvested at the indicated time [0, 6, and 12 hpi (hours post infection)]." (PMID 32922375, 2020). "Two of these upregulated genes are related to damage response and the prevention of infection by retroviruses (ZMAT3 and ZC3HAV1, respectively)." (PMID 32317694, 2020). "Four interferon-stimulated proteins with antiviral function were up-regulated only in the Hep-dG infection group, including RIG-I, ISG15, Zc3hav1, and Irgm1." (PMID 26217322, 2015).